RN7SL309P (RNA, 7SL, cytoplasmic 309, pseudogene)
Gene: Miscellaneous RNA gene on chromosome 11 (65,695,552 to 65,695,837, forward strand). Ensembl gene ENSG00000239356.
Homologues: Orthologues: chimpanzee Metazoa_SRP (99% identical), macaque Metazoa_SRP (90% identical). Paralogues in human: RN7SL2 (84% identical), RN7SL1 (83% identical), RN7SL3 (81% identical), RN7SL709P (80% identical), RN7SL126P (80% identical), RN7SL14P (80% identical), RN7SL444P (79% identical), RN7SL478P (79% identical), RN7SL543P (79% identical), RN7SL664P (79% identical), RN7SL122P (79% identical), Metazoa_SRP (78% identical), and 703 more.